CSNK1A1 (casein kinase 1 alpha 1)
Description:
Casein kinases are operationally defined by their preferential utilization of acidic proteins such as caseins as substrates. It can phosphorylate a large number of proteins. Participates in Wnt signaling. Phosphorylates CTNNB1 at 'Ser-45'. May phosphorylate PER1 and PER2 (By similarity). May play a role in segregating chromosomes during mitosis. May play a role in keratin cytoskeleton disassembly and thereby, it may regulate epithelial cell migration. Acts as a positive regulator of mTORC1 and mTORC2 signaling in response to nutrients by mediating phosphorylation of DEPTOR inhibitor. Acts as an inhibitor of NLRP3 inflammasome assembly by mediating phosphorylation of NLRP3 (By similarity).
Synonyms: CK1; CK1a; CK1alpha; CKIa; CKIalpha; HEL-S-77p; HLCDGP1; PRO2975
Tractability: Small molecule: a structure with a bound ligand is known; a high-quality ligand is known; it belongs to a druggable protein family. PROTAC: it is named in the literature on targeted protein degradation; ubiquitination databases record sites on it; its protein half-life has been measured; a small molecule that binds it is known.
Target class: CK1 protein kinase group; Enzyme; CK1 protein kinase CK1 family; Protein Kinase; Kinase
Gene: Protein-coding gene on chromosome 5 (149,492,982 to 149,551,471, reverse strand). Ensembl gene ENSG00000113712.
Subcellular location: Cytoplasm; Cytoplasm, cytoskeleton, microtubule organizing center, centrosome; Chromosome, centromere, kinetochore; Nucleus speckle; Cytoplasm, cytoskeleton, cilium basal body; Cytoplasm, cytoskeleton, spindle
Subcellular location (Human Protein Atlas): Cytosol
Pathways (Reactome):
Disease: APC truncation mutants have impaired AXIN binding; AXIN missense mutants destabilize the destruction complex; CTNNB1 S33 mutants aren't phosphorylated; CTNNB1 S37 mutants aren't phosphorylated; CTNNB1 S45 mutants aren't phosphorylated; CTNNB1 T41 mutants aren't phosphorylated; Maturation of nucleoprotein; Signaling by GSK3beta mutants; Truncations of AMER1 destabilize the destruction complex
Signal Transduction: Activation of SMO; Beta-catenin phosphorylation cascade; Degradation of GLI2 by the proteasome; Degradation of beta-catenin by the destruction complex; Disassembly of the destruction complex and recruitment of AXIN to the membrane; GLI3 is processed to GLI3R by the proteasome
Cell Cycle: Ubiquitin-Mediated Degradation of Phosphorylated Cdc25A
Gene Ontology:
Molecular function: protein binding; protein serine kinase activity; protein serine/threonine kinase activity; protein kinase activity; ATP binding
Biological process: cellular response to nutrient; Golgi organization; intermediate filament cytoskeleton organization; negative regulation of canonical Wnt signaling pathway; positive regulation of proteasomal ubiquitin-dependent protein catabolic process; positive regulation of Rho protein signal transduction; positive regulation of TORC1 signaling; protein phosphorylation; cell surface receptor signaling pathway; negative regulation of NLRP3 inflammasome complex assembly; proteasome-mediated ubiquitin-dependent protein catabolic process; signal transduction; viral protein processing; Wnt signaling pathway; regulation of Wnt signaling pathway
Cellular component: beta-catenin destruction complex; centrosome; cytoplasm; cytosol; keratin filament; membrane; mRNA cleavage and polyadenylation specificity factor complex; nuclear speck; ciliary basal body; cilium; nucleoplasm; spindle
Genetic constraint (gnomAD): Loss-of-function variants: 5 observed, 30.97 expected, observed/expected ratio (o/e) 0.16, 90% interval 0.083 to 0.34. The upper end of that interval is the gene's LOEUF score, 0.34, which puts it in group 1 of 6, group 1 being the genes least tolerant of losing a copy. Missense variants: 78 observed, 319.72 expected, observed/expected ratio (o/e) 0.24, 90% interval 0.2 to 0.29. Synonymous variants: 105 observed, 115.34 expected, observed/expected ratio (o/e) 0.91, 90% interval 0.78 to 1.07.
Homologues: Orthologues: dog CSNK1A1 (100% identical), guinea pig CSNK1A1 (100% identical), macaque CSNK1A1 (100% identical), pig CSNK1A1 (99% identical), rabbit CSNK1A1 (99% identical), tropical clawed frog csnk1a1 (99% identical), zebrafish csnk1a1 (99% identical), rat Csnk1a1 (99% identical), mouse Csnk1a1 (99% identical), Caenorhabditis elegans kin-19 (83% identical), Drosophila melanogaster CkIalpha (76% identical), Drosophila melanogaster CG7094 (61% identical), and 2 more. Paralogues in human: CSNK1A1L (91% identical), CSNK1D (70% identical), CSNK1E (68% identical), CSNK1G3 (51% identical), CSNK1G2 (51% identical), CSNK1G1 (50% identical), TTBK1 (35% identical), TTBK2 (35% identical), VRK1 (30% identical), VRK2 (28% identical), CDC7 (23% identical), VRK3 (21% identical).
Diseases named in the same sentence as CSNK1A1 in open-access papers:
CSNK1A1 is named in the same sentence as 101 diseases in open-access papers, as found by Europe PMC text mining. Sharing a sentence is not in itself a finding about the gene and the disease. The quoted sentences say what the papers report.
myelodysplastic syndrome (22 papers, 2015 to 2025). A clonal hematopoietic disorder characterized by dysplasia and ineffective hematopoiesis in one or more of the hematopoietic cell lines. "Furthermore, mutation of CSNK1A1 is most commonly associated with myelodysplastic syndromes (5q deletion syndrome) and therefore CK1α has been identified as a promising therapeutic target for these patients." (PMID 39001502, 2024). "Mutations of CSNK1A1, a gene mapping to the commonly deleted region of the 5q‐ syndrome, have been recently described in patients with del(5q) myelodysplastic syndromes (MDS)." (PMID 26085061, 2015). "CSNK1A1 (CK1α) was also identified as a lenalidomide-specific neosubstrate with clinical relevance to del(5q) myelodysplastic syndrome." (PMID 37815734, 2023). "The investigation of the lenalidomide mechanism of action in other hematological malignancies, such as myelodysplastic syndrome with del5q, identified the next neosubstrate of CRBN; a casein kinase 1 α (CK1α; encoded on chromosome 5q by CSNK1A1)." (PMID 36139651, 2022).
myeloma (21 papers, 2015 to 2025). "Overexpression of CSNK1A1 can promote the proliferation and survival of tumor cells by downregulating the expression of CTNNB1 in myeloma; CSNK1A1 and CTNNB1 both function in the classic Wnt/β-catenin signaling pathway." (PMID 32993576, 2020).
colorectal cancer (20 papers, 2007 to 2025). A primary or metastatic malignant neoplasm that affects the colon or rectum. "In a mouse model of colorectal cancer, genetic loss of CKIα (Csnk1a1) in intestinal epithelial cells induces a senescence-associated inflammatory response that efficiently antagonizes the proliferative activity of Wnt signaling and counteracts tumorigenesis." (PMID 32075247, 2020). "For example, the Human Protein Atlas reports high expression of CSNK1A1 as prognostically favourable in colorectal cancer and unfavourable in pancreatic cancer." (PMID 39001502, 2024). "However, nearest research reported that CSNK1A1 overexpression correlates with poor survival in colorectal cancer." (PMID 29793495, 2018). "Low levels of CSNK1A1 may contribute to tumorigenesis and poor prognosis, especially in colorectal cancer according to the data from open-source databases." (PMID 29793495, 2018). "In particular, we identified a small set of genes (in particular VRK1, CSNK1A1, and PIK3R4) that were more dramatically depleted in colorectal cancer cell lines, than a range of leukemia, liver and pancreatic cancer cell lines." (PMID 31891587, 2019).
colon carcinoma (18 papers, 2009 to 2025). "Genomic sequencing of the colon tumor samples confirmed the presence of a missense mutation in the catalytic aspartic acid of CSNK1A1 (GAC→AAC)." (PMID 27031502, 2016). "Recently, in mice Csnk1a1 or CKIα expression has been implicated in colon cancer invasiveness and cell transformation in the gut." (PMID 23739040, 2013). "Loss of function of Csnk1a1 may be related to poor prognosis in colon cancer." (PMID 26829228, 2016). "CSNK1A1 mutations have also been detected in adult T cell leukemia/lymphoma (ATL), clear cell renal cell carcinoma, colon cancer, and esophageal adenocarcinoma." (PMID 29793495, 2018). "The observed MS2 spectrum and elution time for the engineered CSNK1A1 mutant were identical to that observed in the colon tumor sample." (PMID 27031502, 2016).
breast carcinoma (12 papers, 2013 to 2025). "For example, CSNK1A1 has been implicated in various cancers, including liver and breast cancers, where its dysregulation contributes to tumor progression and chemoresistance." (PMID 40128844, 2025). "In addition, alterations in Csnk1a1 function or expression have been implicated in prostate cancer, leukemia, myelodysplatic syndrome, and breast cancer." (PMID 26829228, 2016). "In our study, the high correlation between CSNK1A1 and NFATC3 is associated with poor survival in the ER-negative group, which suggests that pharmacological inhibition of NFATC3 by targeting CSNK1A1 could be of therapeutic interest for breast cancer patients." (PMID 33450402, 2020).
leukemia (11 papers, 2014 to 2025). A malignant (clonal) hematologic disorder, involving hematopoietic stem cells and characterized by the presence of primitive or atypical myeloid or lymphoid cells in the bone marrow and the blood.
lung carcinoma (10 papers, 2012 to 2022). "Overall, in our study we described the use of an innovative integrative genomic approach to identify new candidate genes for lung cancer treatment, namely CSNK1A1, KDM2A, and LTB4R2." (PMID 34298691, 2021). "In addition, this strategy allowed us to identify three target genes that are poorly characterized and still require biological validation in lung cancer: CSNK1A1, KDM2A, and LTB4R2." (PMID 34298691, 2021). "We identified and validated a set of novel druggable non-oncogene vulnerabilities preferentially related to different lung cancer histotypes; dependency on KDM2A is associated with AD and SCLC, dependency on CSNK1A1 is associated with AD, and dependency on LTB4R2 is associated with SCC." (PMID 34298691, 2021). "Furthermore, the combination of NIFK (MKI67IP) and CK1α (CSNK1A1) may represent a superior prognostic indicator for lung cancer (p = 0.01)." (PMID 26984280, 2016). "Through this approach, we identified and validated CSNK1A1, KDMA2, and LTB4R2 as new druggable vulnerabilities in lung cancer." (PMID 34298691, 2021). "Through this analysis, we identified CSNK1A1, KDM2A, and LTB4R2 as relevant druggable essentiality genes in lung cancer." (PMID 34298691, 2021). "The HIF, TGM2, CSNK1A1, CSNK2A1, CTNNA1, NAMPT)/Visfatin, TNFRSF1A, ETS1 and SRC-1 were down-regulated and proposed as the biomarkers for lung cancer." (PMID 23122428, 2012). "Expression analysis reveals that hypoxia induced lung cancer related biomarkers, HIF and its modulating proteins (TGM2, CSNK1A1, CTNNA1, NAMPT/Visfatin, TNFRSF1A, ETS1, SRC-1, FN1, APLP2, DMBT1/SAG, AIB1 and AZIN1) are significantly down regulated." (PMID 23122428, 2012). "We reasoned that CSNK1A1, KDM2A, and LTB4R2 dependencies could become therapeutic intervention points in lung cancer, so we proceeded with further characterization." (PMID 34298691, 2021).
melanoma (10 papers, 2011 to 2021). A malignant, usually aggressive tumor composed of atypical, neoplastic melanocytes. "The total alteration frequency including CNAs and mutations is generally rather low ranging from 4.8% in clear cell renal cell carcinoma (ccRCC) for CSNK1A1 over 9.5% in liver cancer for CSNK1D to 3.8% for CSNK1E in melanoma tumors." (PMID 25306547, 2014). "Furthermore, the mechanisms of regulation of CSNK1A1 in cancer are not well understood, although promoter methylation in melanoma has been reported." (PMID 32029502, 2020). "The analysis focused only on CSNK1A1, CSNK1D, and CSNK1E, not on CSNK1G; CSNK1A1 alterations are dominant in clear cell renal cell carcinoma, and pancreas cancer, CSNK1D in liver and sarcoma, and CSNK1E in melanoma and liver." (PMID 33861751, 2021).
acute myeloid leukemia (9 papers, 2015 to 2025). Acute myeloid leukemia (AML) is a group of neoplasms arising from precursor cells committed to the myeloid cell-line differentiation. "Csnk1a1 (CK1a) is one of the seven subfamilies of casein kinase 1, which is necessary for the survival of acute myeloid leukaemia cells." (PMID 34216174, 2021). "At present, Csnk1a1 has become a potential therapeutic target in many tumours, including chronic lymphocytic leukaemia, acute myeloid leukaemia 20 and multiple myeloma." (PMID 34216174, 2021).
glioblastoma (5 papers, 2017 to 2025). The most malignant astrocytic tumor (WHO grade IV). "Studies on glioblastoma multiforme cells have shown that the increase in CXCL1 expression by ionizing radiation is casein kinase 1 alpha 1 (CK1α) dependent and dependent on an increase in inhibitor of NF-κBζ (IκBζ) expression." (PMID 40427171, 2025). "In this study, we evaluated the effect of Csnk1a1 inhibition on the proliferation of glioblastoma, inflammatory factors and sensitivity to radiotherapy." (PMID 34216174, 2021). "However, further research strategies for targeting Csnk1a1 to treat glioblastoma should address the roles of TP 53 and NF‐κB signalling pathways in the regulation of inflammatory cytokine secretion by glioma cells." (PMID 34216174, 2021).
colorectal tumors (3 papers, 2018 to 2022). "Csnk1a1 downregulation induces a senescence-associated inflammatory response with growth arrest in colorectal tumors." (PMID 35366793, 2022). "Epithelial cells lacking Csnk1a1 also exhibits many of the characteristics of human colorectal tumors, particularly induces DNA damage responses and cellular senescence." (PMID 32317933, 2020).
COVID-19 (3 papers, 2022 to 2023). A disease caused by infection with severe acute respiratory syndrome coronavirus 2. "Microthrombi-positive versus microthrombi-negative COVID-19 comparisons yielded 4 tier 1 targets: PIP5K1A, STAT3, and VEGFA in fibroblasts and CSNK1A1 in pericytes." (PMID 34905515, 2022).
glioma (3 papers, 2021 to 2024). A benign or malignant brain and spinal cord tumor that arises from glial cells (astrocytes, oligodendrocytes, ependymal cells). "We identified linear associations between the expression of the DKK3, CTNNB1, FSTL1, and CSNK1A1 genes classified by the WHO glioma grade." (PMID 37149563, 2023). "Here, we reported that Csnk1a1 was significantly overexpressed in glioma, indicating an important role in the growth of glioma cells." (PMID 34216174, 2021). "Csnk1a1 was also highly expressed in glioma tissue samples using GEPIA analysis in the TCGA database." (PMID 34216174, 2021). "However, when the relationship between FSTL1 and CSNK1A1 was estimated, the positive correlation between FSTL1 and CSNK1A1 was stronger in GBM than in grade II or III glioma." (PMID 37149563, 2023). "When the relationship between DKK3 and CSNK1A1 was calculated, a significant negative association was shown between DKK3 and CSNK1A1 in grade II glioma." (PMID 37149563, 2023). "Therefore, based on our findings, we hypothesized that CSNK1A1 may change its role in degrading β-catenin and rather activate β-catenin signaling in the glioma environment." (PMID 37149563, 2023). "Therefore, we hypothesized that inhibiting Csnk1a1 activity could promote radiotherapy sensitivity in glioma." (PMID 34216174, 2021). "We calculated the correlations between the expressions levels of the DKK3, CTNNB1, FSTL1, and CSNK1A1 genes and eight immune cell fractions in grade II or III glioma and GBM." (PMID 37149563, 2023). "On the other hand, when the relationships between CSNK1A1 and CTNNB1 and between FSTL1 and CTNNB1 were estimated, positive correlations with similar slopes were shown in both grade II or III glioma and GBM." (PMID 37149563, 2023). "We also observed that as the grade of glioma increased, DKK3 expression showed a tendency to be more strongly positively correlated with the expression of CTNNB1, FSTL1, and CSNK1A1, which are related to the Wnt/β-catenin pathway." (PMID 37149563, 2023). "Based on previously published studies and our current findings, we herein present schematic illustrations of the hypothetical role of DKK3 in glioma progression considering its interaction with CTNNB1, FSTL1, and CSNK1A1, which are involved in the Wnt/β-catenin signaling pathway." (PMID 37149563, 2023). "Interestingly, there were Wnt/β-catenin-related genes whose mRNA expression levels were noticeably increased in GBM compared with grade II and III glioma, and those genes were catenin beta 1 (CTNNB1), follistatin-like 1 (FSTL1), and casein kinase 1 alpha 1 (CSNK1A1)." (PMID 37149563, 2023). "However, in grade III glioma, the relationship between DKK3 and CSNK1A1 was not statistically significant, and in grade IV GBM, the association between DKK3 and CSNK1A1 showed a significant positive correlation." (PMID 37149563, 2023).
non-small cell lung carcinoma (3 papers, 2018 to 2025). A group of at least three distinct histological types of lung cancer, including non-small cell squamous cell carcinoma, adenocarcinoma, and large cell carcinoma. "Previous studies have shown that CSNK1A1 inhibits the growth of non-small cell lung cancer by inducing autophagy through the AKT/FOXO3a/ATG7 pathway." (PMID 41213929, 2025). "Another study showed that CSNK1A1 inhibits the growth of non-small cell lung cancer by inducing autophagy via the AKT/FOXO3a/ATG7 pathway without affecting mTOR activity." (PMID 41213929, 2025). "For example, casein kinase 1 alpha 1 activates PTEN/AKT/FOXO3A/ATG7 axis-mediated autophagy, inhibiting the growth of non-small cell lung cancer." (PMID 36016573, 2022).